ISLR (immunoglobulin superfamily containing leucine rich repeat)
Synonyms: HsT17563; Meflin
Tractability: Antibody: UniProt places it where antibodies can reach, with high confidence; its Gene Ontology location is reachable by antibodies, with high confidence; UniProt predicts a signal peptide or a membrane-spanning region; the Human Protein Atlas places it where antibodies can reach. PROTAC: its protein half-life has been measured.
Gene: Protein-coding gene on chromosome 15 (74,172,414 to 74,176,872, forward strand). Ensembl gene ENSG00000129009.
Subcellular location: Secreted
Subcellular location (Human Protein Atlas): Plasma membrane; Golgi apparatus; Predicted to be secreted
Pathways (Reactome):
Hemostasis: Platelet degranulation
Gene Ontology:
Biological process: cell adhesion
Cellular component: extracellular exosome; extracellular region; platelet alpha granule lumen
Genetic constraint (gnomAD): Loss-of-function variants: 7 observed, 17.62 expected, observed/expected ratio (o/e) 0.4, 90% interval 0.22 to 0.75. The upper end of that interval is the gene's LOEUF score, 0.75, which puts it in group 3 of 6, group 1 being the genes least tolerant of losing a copy. Missense variants: 466 observed, 544.65 expected, observed/expected ratio (o/e) 0.86, 90% interval 0.79 to 0.92. Synonymous variants: 244 observed, 246.67 expected, observed/expected ratio (o/e) 0.99, 90% interval 0.89 to 1.1.
Homologues: Orthologues: chimpanzee ISLR (99% identical), macaque ISLR (97% identical), dog ISLR (91% identical), pig ISLR (89% identical), rat Islr (87% identical), mouse Islr (86% identical), guinea pig ISLR (86% identical), rabbit ISLR (81% identical), zebrafish islr2 (42% identical). Paralogues in human: ISLR2 (48% identical), LRRN4 (19% identical), LRRN4CL (7% identical).
Diseases named in the same sentence as ISLR in open-access papers:
ISLR is named in the same sentence as 20 diseases in open-access papers, as found by Europe PMC text mining. Sharing a sentence is not in itself a finding about the gene and the disease. The quoted sentences say what the papers report.
colon cancer (4 papers, 2021 to 2023). "Inhibition of the EMT signaling pathway can suppress the growth, migration, and invasion of colon cancer cells and weaken the pro-tumor properties of ISLR overexpression on colon cancer progression." (PMID 37427332, 2023). "Meflin (ISLR) is defined as a new cell surface marker for cancer-restraining CAFs in pancreatic and colon cancers." (PMID 36092895, 2022). "It has previously been reported that low levels of ABI1 and high levels of ADAT2 or ISLR, result in an increase in extracellular matrix (ECM) degradation, migration, and cell invasion in colon cancer." (PMID 37158593, 2023). "Furthermore, analysis of expression microarray data from 556 patients with primary colon cancer confirmed that the GREM1-high and ISLR-low groups each independently exhibited poor overall survival." (PMID 33197448, 2021).
colorectal cancer (4 papers, 2021 to 2024). A primary or metastatic malignant neoplasm that affects the colon or rectum. "According to previous literatures, ISLR promotes colorectal cancer (CRC) progression; SNAIL1 promotes GC cell proliferation and migration; and CHEK1 is up-regulated in lung cancer and inhibits the radiotherapy sensitivity of GC cells." (PMID 35739527, 2022). "In patients with colorectal cancer, the augmentation of CAFs secreting the BMP signaling antagonist Gremlin 1 is associated with poor survival, whereas CAF secreting the BMP signaling activator ISLR inhibit colorectal cancer progression." (PMID 39327633, 2024). "(A) T1 colorectal cancer (CRC) samples from a set of 47 cases were used to verify the abundance of ABI1, ITPR2, RHOT2, ATAD2, and ISLR." (PMID 37158593, 2023).
gastric cancer (4 papers, 2020 to 2023). A primary or metastatic malignant neoplasm involving the stomach. "ISLR, a member of the immunoglobulin superfamily, is highly expressed in gastric cancer tissue and associated with poor prognosis of patients." (PMID 34900998, 2021). "Unexpectedly, during the survival analysis of gastric cancer patients treated with a 5-Fu-based adjuvant, high expression of the ISLR gene was linked to a better prognosis than low expression of the ISLR gene." (PMID 32612640, 2020). "We attempted to study the potential mechanism of the ISLR gene in the pathogenesis of gastric cancer in terms of gene mutation and copy number variation." (PMID 32612640, 2020). "As a result, ISLR was highly expressed in gastric cancer and was associated with poor prognosis." (PMID 37427332, 2023). "ISLR is highly expressed in gastric cancer and is associated with poor prognosis." (PMID 37427332, 2023). "Surprisingly, for the 158 gastric cancer cases treated with 5-Fu-based adjuvant therapy, a high level of ISLR expression was linked to a better clinical prognosis than a low level of ISLR expression (HR = 0.63, P = 0.013), indicating a possible connection of ISLR expression with drug sensitivity." (PMID 32612640, 2020). "This study aims to investigate the immunoglobulin superfamily containing leucine-rich repeat (ISLR) expression in gastric cancer (GC) and ISLR’s underlying mechanisms regulation of GC progression." (PMID 35653801, 2022). "The expression of ISLR was increased in gastric cancer cells compared with that in normal gastric epithelial cells, and ISLR expression was the highest in AGS cells." (PMID 37427332, 2023). "This study is the first to demonstrate the suppressive role of ZBTB16 silencing in gastric cancer and present a novel regulatory relationship between ISLR and MGAT5 in gastric cancer." (PMID 37427332, 2023). "Research shows that ISLR is highly expressed in gastric cancer tissues, which is closely related to clinical prognosis." (PMID 37427332, 2023). "The present study attempted to investigate the possible oncogenic roles of the ISLR gene in the pathogenesis and prognosis of gastric cancer." (PMID 32612640, 2020). "ISLR interacted with MGAT5 to promote the malignant progression of gastric cancer." (PMID 37427332, 2023). "GEPIA database indicated that ISLR was highly expressed in the tissues of gastric cancer patients." (PMID 37427332, 2023). "Based on the available datasets of gastric cancer cases collected by TCGA and GEO, for the first time, we found a statistical correlation between high expression of the ISLR gene and poor overall survival, disease-free survival, first progression, and post-progression survival." (PMID 32612640, 2020). "Gene ontology (GO) and Kyoto Encyclopedia of Genes and Genomes (KEGG) analysis have shown that the ISLR gene is involved in gastric cancer, the potential molecular mechanism of which may include DNA methylation, epithelial-mesenchymal transition (EMT), and immune cell infiltration." (PMID 37427332, 2023). "Therefore, the present study aimed to investigate the role of the ISLR gene in gastric cancer and examine whether ISLR could interact with MGAT5 to affect the malignant progression of gastric cancer." (PMID 37427332, 2023). "The present study aimed to investigate the role of the immunoglobulin superfamily containing leucine-rich repeat (ISLR) gene in gastric cancer and examine whether ISLR could interact with N-acetylglucosaminyltransferase V (MGAT5) to affect the malignant progression of gastric cancer." (PMID 37427332, 2023). "The present study covered the effects of ISLR on gastric cancer cell proliferation, invasion, migration, and EMT to support the oncogenic role of ISLR in the malignant behaviors of gastric cancer cells, which could offer a potential biomarker for the diagnosis and treatment of gastric cancer." (PMID 37427332, 2023).
gastric cancer (continued). "In this study, we only discussed the regulatory effect of ISLR and MGAT5 on the progression of gastric cancer cells." (PMID 37427332, 2023). "MGAT5 overexpression weakened the effects of ISLR knockdown on suppressing the viability, proliferation, migration, invasion, and EMT of gastric cancer cells." (PMID 37427332, 2023). "The expression of ISLR and MGAT5 in human normal gastric epithelial cells and human gastric cancer cells, and the transfection efficiency of ISLR interference plasmids and MGAT5 overexpression plasmids were all detected by reverse transcription-quantitative PCR (RT-qPCR) and western blot." (PMID 37427332, 2023). "Taken together, the expression of ISLR and MGAT5 was increased in gastric cancer cells and interference with ISLR inhibited the proliferation, invasion, migration, and EMT of gastric cancer cells, which could be reversed by MGAT5 overexpression." (PMID 37427332, 2023). "Collectively, these results indicated that the expression level of the ISLR gene in gastric cancer cases was higher than that in negative controls, which suggests the potential role of the ISLR gene in the etiology of gastric cancer." (PMID 32612640, 2020).
breast carcinoma (3 papers, 2016 to 2024). "Given that loss of stromal BMPR2 expression increases cytokine production in a mouse model of breast cancer, further studies are warranted to investigate whether mesenchymal BMP signaling, modulated by GREM1 and ISLR, could also be involved in shaping the immunosuppressive tumor microenvironment." (PMID 33197448, 2021).
non-small cell lung carcinoma (2 papers, 2022 to 2023). A group of at least three distinct histological types of lung cancer, including non-small cell squamous cell carcinoma, adenocarcinoma, and large cell carcinoma. "In non-small cell lung cancer (NSCLC), silencing ISLR increased the apoptotic rate of cells." (PMID 36136577, 2022).
bone metastasis (1 paper, 2022). Transfer of a neoplasm from its primary site to bones. "The ISLR gene was found to be a favorable factor for PRAD bone metastasis survival, with the survival rate in the high-risk group being much lower than that in the low-risk group." (PMID 35783639, 2022). "We identified ISLR as a potential biomarker for PRAD bone metastasis." (PMID 35783639, 2022).
lymph node metastasis (1 paper, 2022). "In addition, ISLR expression was correlated with tumor size, lymph node metastasis, and clinical stage." (PMID 35653801, 2022). "ISLR expression was correlated with tumor size, lymph node metastasis, and clinical stage, while ISLR expression had no relation to age or gender." (PMID 35653801, 2022).
Myocardial fibrosis (1 paper, 2024). "Conversely, mice lacking ISLR displayed marked myocardial fibrosis, indicating a crucial role for ISLR in the repair of myocardial damage and fibrosis." (PMID 39062507, 2024).
osteoporosis (1 paper, 2025). A condition of reduced bone mass, with decreased cortical thickness and a decrease in the number and size of the trabeculae of cancellous bone (but normal chemical composition), resulting in increased fracture incidence. "ISLR was on the other side evaluated as a potential target for osteoporosis in mice in this 2024 study, where ISLR knockout mice showed enhanced bone formation." (PMID 40304052, 2025).
rectal cancer (1 paper, 2021). A primary or metastatic malignant neoplasm that affects the rectum. "To investigate the clinical significance of GREM1 and ISLR expression in CRC CAFs, we evaluated GREM1 and ISLR expression by ISH in 53 rectal cancer surgical samples." (PMID 33197448, 2021).
tumor (10 papers, 2016 to 2025). "ISLR is also downregulated and negatively correlated with Tumor Mutation load (TMB)." (PMID 41574107, 2025). "ISLR was overexpressed in both GC cell lines and tumor tissues, and our study first showed that silencing of ISLR inhibited GC cell growth and metastasis by reversing EMT." (PMID 35653801, 2022). "TCGA results showed that ISLR expression was higher in GC tumor tissues compared to normal tissues, and its expression levels were related to lymph node metastasis, tumor size, and clinical stage." (PMID 35653801, 2022). "We observed that ISLR expression was increased in both GC cells and tumor tissues, and our study, for the first time, indicated that ISLR silencing inhibited cell growth and metastasis by regulating the EMT pathway." (PMID 35653801, 2022). "The results suggested that ISLR was highly expressed in tumor cell lines (HGC-27, MKN-45, MGC-803, and AGC cells), with the expression in HGC-27 cells being the most pronounced and that in AGS cells being the lowest." (PMID 35653801, 2022). "Our results indicated that the ISLR expression in GC tumor tissues was higher compared with that in normal tissues." (PMID 35653801, 2022). "The genes COL3A1, ISLR, and IFITM1 are specific for vascular cells and show up-regulation in the tumor and down-regulation in the periphery." (PMID 35327982, 2022). "Principal component analysis and random forest analysis were employed to further screen for six hub genes, including ISLR, COL1A2, CDH11, SPARC, COL3A1, and COL1A1, which exhibited a good ability to differentiate between tumor and normal samples." (PMID 32612640, 2020). "PTC and FTC tumours presented a group of common dysregulated proteins including SOD3, ISLR, biotinidase, polymerase I and transcript release factor (cavin-1), TFF3, alpha(B)-crystallin (CryAB), AGR2, tenascin and 14-3-3 gamma." (PMID 27025787, 2016). "Moreover, several genes (such as BCAR3, GNAS, ISLR and RASGRP3) exhibited opposite patterns of AS events of a parent gene in tumor and normal tissues." (PMID 31695792, 2019).
cancer (8 papers, 2017 to 2024). A tumor composed of atypical neoplastic, often pleomorphic cells that invade other tissues. "Previous reports have demonstrated that ISLR is widely expressed in the skeletal muscle, heart, thyroid, brown adipose tissue, cancer-associated fibroblasts, and various cancer cells." (PMID 38786060, 2024). "ISLR was the first identified marker of cancer-suppressing TAFs in human and mouse pancreatic ductal carcinoma (PDAC)." (PMID 35410257, 2022). "ISLR is a potential therapeutic target for reprogramming TAFs for cancer therapy." (PMID 35410257, 2022). "By targeting the upstream determinants of mesenchymal expression, such as TGF-β and FOXL1 or by targeting the downstream drivers of BMP signaling such as GREM1 and ISLR, one may identify new approaches to prevent and treat cancer." (PMID 33197448, 2021). "ISLR/Meflin is a newly discovered surface and secreted pluripotency-related protein whose over-expression has been described in cancer stroma and fibrotic diseases, and a recent immunoprecipitation study has demonstrated its interaction with receptor tyrosine kinases (RTKs) such as EGFR and PDGFRA." (PMID 28415643, 2017). "Interestingly, GREM1+ CAFs were spatially distinct from ISLR+ CAFs in desmoplastic human CRC, with ISLR+ CAFs located in closer proximity to cancer cells than GREM1+ CAFs." (PMID 33197448, 2021). "CUVs from the genes MYO1E, SARDH and ISLR appeared in two distinct individuals with cancer from this non-Caucasian cohort, while CUVs from PCDHB16 and known CPG BMPR1A appeared in a single individual with cancer." (PMID 32778766, 2020).
heart disease (1 paper, 2024). "Furthermore, understanding the potential interplay between IGFBP3, ISLR, SOST, and paracrine/autocrine response is a pivotal step in the identification of new or improved drug targets for the treatment of heart disease." (PMID 39430425, 2024).
ISLR also shares sentences with these, for which no sentence is quoted: lung carcinoma (2 papers); Cirrhosis (1); diffuse gastric adenocarcinoma (1); ovarian carcinoma (1); psoriasis (1); skin cutaneous melanoma (1); triple-negative breast carcinoma (1).